TRPV1 (transient receptor potential cation channel subfamily V member 1)
Diseases named in the same sentence as TRPV1 in open-access papers (continued):
Sharing a sentence is not in itself a finding about the gene and the disease.
fibromyalgia (continued). "Finally, we observed lower colocalizations of TRPV1 and pERK in the normal mouse cerebellum than in the fibromyalgia group." (PMID 38474148, 2024). "Finally, we showed that S100B and HMGB1 regulate TRPV1 and its signalling pathways and propose TRPV1 as a potential therapeutic target for fibromyalgia." (PMID 35341159, 2022). "We hypothesized that EA attenuates fibromyalgia-like hyperalgesia by acting on TRPV1 in the mice brain." (PMID 35341159, 2022). "EA at ST36 might relieve fibromyalgia pain by directly inhibiting neuronal TRPV1 or TRPV1 on glial cells to interrupt the signalling pathway." (PMID 35341159, 2022). "Besides, Trpv1 deletion prevented the increase in pERK expression in fibromyalgia mice and displayed positive tendencies toward EA treatment in the DRG and spinal cord of fibromyalgia mice." (PMID 34082798, 2021). "It remains unknown whether electroacupuncture (EA) attenuates fibromyalgia pain or affects the TRPV1 pathway." (PMID 34082798, 2021). "Thus, probing the molecular determinants that contribute to the non-ASIC3, non-TRPV1 acid signaling will be a key step to reveal the mystery of fibromyalgia, especially for individuals who have soreness phenotypes and are resistant to acupuncture analgesia." (PMID 30486810, 2018). "In the fibromyalgia model induced by intermittent cold stress (ICS), electroacupuncture treatment and TRPV1 deletion reversed the increase in IL-6 in female mice plasma and reduced heat and mechanical hyperalgesia, indicating the role of IL-6 in electroacupuncture-treated fibromyalgia." (PMID 40332543, 2025). "An increased expression of these kinases was observed in fibromyalgia mice compared to the normal group, which was diminished by 2 Hz EA treatment at ST36 acupoints as well as in Trpv1−/− mice (# p < 0.05, n = 6)." (PMID 40430245, 2025). "In this study, we showed that CB1 expression was markedly reduced in fibromyalgia-affected DRG, leading to an overactivation of TRPV1 nociceptive signaling pathways." (PMID 40430245, 2025). "We showed increased TRPV1 signaling and decreased CB1 expressions in the vlPAG in a fibromyalgia pain mouse model." (PMID 40430245, 2025). "We next determined the lower colocalizations of TRPV1 and pERK in the normal mouse SSC than in the fibromyalgia group." (PMID 38474148, 2024). "Although the molecular identity of the ASIC3‐, TRPV1‐independent acid sensors is unknown, a possible candidate is ASIC1a, because ASIC1a can mediate anti‐nociceptive signalling in muscle afferents in response to dextrose prolotherapy in the acid‐induced fibromyalgia model." (PMID 37417654, 2024). "Electroacupuncture inhibited the hyper-excitable of the dorsal root ganglion neurons and expression of TRPV1 and TRPV4 in the spinal cord of a murine model of fibromyalgia." (PMID 33002009, 2020). "In a mouse model of fibromyalgia induced by repeated intramuscular acid injections, ASIC3 and TRPV1 play essential roles in acute pain induction, hyperalgesic priming, and the development of chronic pain." (PMID 30486810, 2018). "Furthermore, the chemogenetic inhibition of the paraventricular nucleus significantly attenuated the overexpression of the TRPV1 pathway in Hypo and PAG in fibromyalgia mice (n = 6)." (PMID 40430245, 2025). "In addition, there were lower colocalizations of TRPV1 and pERK in the normal mouse ACC than in the fibromyalgia group." (PMID 38474148, 2024). "The current study showed increased protein levels of TRPV1 and related factors in the ascending pain pathway, including the thalamus, SSC, ACC, and mPFC in fibromyalgia mice, which EPA administration could decrease." (PMID 38474148, 2024). "Our recent results suggested that TRPV1, which is expressed on neuronal and non-neuronal cell membranes, is the main receptor modulating the fibromyalgia pain signalling pathway." (PMID 35341159, 2022).
fibromyalgia (continued). "The present study aimed to investigate whether EA reduces fibromyalgia pain by inhibiting the HMGB1, S100B, and TRPV1 signalling pathways in the mouse brain." (PMID 35341159, 2022). "Thus, here we propose that the soreness phenotype of fibromyalgia is an imbalanced acid signaling between acid-induced nociception and acid-mediated anti-nociception, mainly due to impaired non-ASIC3, non-TRPV1 acid signaling." (PMID 30486810, 2018). "To examine the efficacy of EA against fibromyalgia-like mechanical and thermal hyperalgesia and the potential effects of CB1 channel signaling, we established ICS-induced fibromyalgia model mice on the wild-type and Trpv1−/− backgrounds and conducted von Frey hair and Hargreaves tests." (PMID 41007675, 2025). "Notably, these alterations could be reversed by 2 Hz EA treatment and TRPV1 knock out, suggesting the pivotal role of CB1-Trpv1 interactions in fibromyalgia pain modulation." (PMID 40430245, 2025). "The heart-protective effect of acupuncture in fibromyalgia may not be through the TRPV1 pathway." (PMID 28245860, 2017). "Although RNA-seq showed that TRPV1 was the most highly upregulated gene after J2H-1702 treatment of TGF-β1-induced LX2 cells, we saw no significant change in the expression of TRPV1 and ADRA1A, both of which are fibromyalgia-related genes, following J2H-1702 treatment in TGF-β1-treated LX2 cells." (PMID 36446766, 2022).
myocardial infarction (22 papers, 2013 to 2026). Gross necrosis of the myocardium, as a result of interruption of the blood supply to the area, as in coronary thrombosis. "We previously showed that TRPV1 loss aggravates inflammation following myocardial infarction, impairs lesion healing, promotes myocardial fibrosis, and leads to poor ventricular remodeling." (PMID 36045746, 2022). "Our previous studies have shown that TRPV1 deficiency impairs post-ischaemic recovery and increases inflammation and cardiac remodelling in isolated perfused hearts after myocardial infarction." (PMID 34040539, 2021). "This is in contrast to a study showing that intrathecal shRNA-based silencing or pharmacological inhibition of TRPV1 leads to a reduction in myocardial infarct size in rats undergoing 30 min ischemia followed by 2 h reperfusion." (PMID 36768836, 2023). "Chronic cardiac TRPV1 afferent signaling following myocardial infarction promotes arrhythmogenic events." (PMID 38254656, 2023). "In this regard, several studies have also positioned TRPV1 as a target of interest in the strategies against myocardial infarction (MI)." (PMID 37759544, 2023). "The authors concluded that the high-fat diet reduced the cardiac postischemic recovery by decreasing TRPV1 expression, increasing the likelihood of having a myocardial infarction." (PMID 35011580, 2021). "Huang and his colleagues reported that TRPV1 plays a protective role in cardiac remodeling that resulted from myocardial infarction." (PMID 25152753, 2014). "In contrast to profibrotic effects, TRPV1 has also been shown to be cardioprotective against post myocardial infarction, since TRPV1 null-mutant mice had a reduced ejection fraction and a high mortality rate, and were more susceptible to myofibroblast activation and fibrinogenesis." (PMID 36277180, 2022). "Transient receptor potential vanilloid type 1 (TRPV1), a specific receptor for capsaicin, exerts a protective role in cardiac remodeling that resulted from myocardial infarction, and peroxisome proliferation-activated receptors δ (PPAR-δ) play an important role in metabolic myocardium remodeling." (PMID 25152753, 2014). "Similarly, in another study characterizing TRPV1 involvement in modulating the effect of TGFβR activation by myocardial infarction (MI) on survival, it was shown that TRPV1 has instead a protective role in the healing process by reducing fibrosis and improving contractile performance." (PMID 24098582, 2013). "Rather, it downregulates the TRPV1/CaMK/CREB/CGRP and TGF-β1/Smad signaling pathways, providing protection against myocardial infarction and fibrosis." (PMID 39712736, 2024). "Intrathecal injection of the TRPV1 antagonist Capsazepine (CPZ) can inhibit TRPV1 activation and reduce the size of myocardial infarction." (PMID 38692008, 2024). "It was shown to improve cardiac function in mice post-myocardial infarction by enhancing mitophagy through the Pink1/Parkin signaling pathway, and to improve cardiac function in STZ-induced diabetic mice by promoting AGTR1/TRPV1-mediated autophagy." (PMID 41178953, 2025). "Related to the reduction of troponin I by CAP, it has already been demonstrated that TRPV1 knockout mice had higher plasma troponin concentrations after myocardial infarction compared to animals in which TRPV1 was not silenced." (PMID 39339783, 2024). "Second, in the discovery cohort, it was not distinguished between subgroups of myocardial infarction and nonmyocardial infarction while the function of TRPV1 may be different in different states of the same disease." (PMID 35905222, 2022).
Insulin resistance (20 papers, 2014 to 2025). Increased resistance towards insulin, that is, diminished effectiveness of insulin in reducing blood glucose levels. "The minor alleles of two TRPV1 variants rs161364 and rs8065080 are associated with reduced insulin resistance and decreased risk of T2D." (PMID 32168890, 2020). "In mice, loss of TRPV1 increases obesity and insulin resistance induced by a high-fat-diet and aging." (PMID 32168890, 2020). "The activation of TRPV1 probably decreased β-amyloid plaques by inhibiting tau phosphorylation and it may be associated with decreasing peripheral insulin resistance." (PMID 25755673, 2015). "Anyway, a role for IGF-1 in pain regulation via TRPV1 modulation is even more plausible when considering the protective role of insulin in diabetic painful neuropathy and the TRPV1 overexpression found in case of insulin resistance." (PMID 39940997, 2025). "For example, insulin can sensitize TRPV1 channels in sensory neurons of the pancreas, while TRPV1 antagonists can increase insulin secretion and improve insulin resistance in diabetic mice." (PMID 38983093, 2023). "Firstly, SA treatment attenuated renal inflammation and improved insulin resistance in both obese WT and TRPV1−/− mice, indicating that the beneficial effects of SA on insulin sensitivity are independent of TRPV1." (PMID 34069822, 2021). "Capsaicin is a specific transient receptor potential vanilloid 1 (TRPV1) agonist which was proved to ameliorate insulin resistance." (PMID 28225806, 2017). "However, it was shown that the TRPV1 agonist capsaicin reduces obesity-induced inflammation, insulin resistance and hepatic steatosis in obese mice fed a high-fat diet (HFD), and reduces fasting blood glucose levels (Refs 18, 19)." (PMID 38659380, 2024). "If this observation holds true in T2DM patients, TRPV1 antagonists may be promising drug candidates to treat impaired glucose tolerance, insulin secretion, and insulin resistance." (PMID 31344877, 2019). "Thus, TRPV1 agonists such as capsaicin may prevent brain insulin resistance by the activation of insulin/IGF-1 signaling." (PMID 25755673, 2015). "HFD-fed WT mice and TRPV1−/− mice (HFD ± CAP) exhibited elevated HOMA-IR scores, indicating marked insulin resistance." (PMID 40864772, 2025). "In rodent models of T2DM, pharmacological blockade of TRPV1 by small-molecule antagonists inhibited calcitonin gene-related peptide (CGRP) secretion, stimulated insulin secretion, reduced insulin resistance and prevented disease progression (Refs 15, 16, 17)." (PMID 38659380, 2024). "However, TRPV1−/− mice on HFD ± CAP exhibited only a modest decline in blood glucose levels after insulin injection, indicating persistent insulin resistance and a lack of CAP efficacy in the absence of TRPV1." (PMID 40864772, 2025).
Pain (20 papers, 2007 to 2025). An unpleasant sensory and emotional experience associated with actual or potential tissue damage, or described in terms of such damage. "Moreover, the TRPV1 rs8065080 polymorphism has been found to significantly affect heat pain thresholds in patients with neuropathic pain and they have also been linked to changes in mechanical pain sensitivity and mechanical hypesthesia." (PMID 37509416, 2023). "Thus, the variant TRPV1 1911A>G may prevent from peripheral and secondary central sensitisation in patients with chronic neuropathic pain." (PMID 21468319, 2011). "This increased TRPV1 expression contributed to the development of mechanical allodynia and thermal hyperalgesia in oxaliplatin-induced peripheral neuropathic pain rats." (PMID 33806325, 2021). "The link between TLR4 and TRPV1 in pain conditions, including paclitaxel-induced peripheral neuropathic pain, has been well documented." (PMID 31775332, 2019). "On the other hand, vitamin D inhibits TRPV1 channels which are involved in thermal hyperalgesia only in the acute phase of neuropathic pain." (PMID 31731694, 2019). "Rodent studies support that some anti-cancer drugs are able to generate pain syndromes via the actions of other TRP family members including TRPV1 and TRPV4." (PMID 29084244, 2017). "Transient receptor potential vanilloid 1 (TRPV1) plays a crucial role in neuropathic pain and influences the plasticity of neuronal connectivity." (PMID 28740739, 2017). "The discovery of TRPV1 and its obvious role in pain diseases triggered the development of novel therapeutic strategies to suppress nociception by targeting TRPV1, including the development of both agonists and antagonists of TRPV1." (PMID 24288041, 2011). "Further, the research findings indicate that sodium, potassium, and calcium ion channels, in conjunction with diverse transient receptor potential families (e.g., TRPA1, TRPM8, and TRPV1), play a pivotal role in the pathophysiology of oxaliplatin-induced neuropathic pain." (PMID 40649805, 2025). "In this study, we explored the involvement of TRPV1 and the MOR-NMDAR complex in the antiallodynic effect of LMH-2 in hyperglycemic mice with neuropathic pain." (PMID 40266532, 2025).
Parkinson disease (19 papers, 2018 to 2026). A progressive degenerative disorder of the central nervous system characterized by loss of dopamine producing neurons in the substantia nigra and the presence of Lewy bodies in the substantia nigra and locus coeruleus. "Recent studies have shown the strong pathogenetic associations of TRPV1 with neurodegenerative diseases (NDs), in particular Alzheimer’s disease (AD), Parkinson’s disease (PD) and multiple sclerosis (MS) via regulating neuroinflammation." (PMID 38202764, 2023). "Injections of 6-OHDA into the striatum of the mouse brain have significantly changed the thermal sensitivity threshold and caused mechanical allodynia inherent in Parkinson’s disease, accompanied by a significant increase in the TRPV1 expression in mice with 6-OHDA lesion." (PMID 33802055, 2021). "For the protective effects, TRPV1 suppressed the oxidative stress and enhanced the endogenous production of a neurotrophic factor in the neurodegeneration diseases including Parkinson’s disease, vascular dementia, and Huntington’s disease." (PMID 38180747, 2024). "Benefits of the CBR/TRPV1 axis for neurodegenerative diseases has been suggested by some studies due to CBRs and TRPV1 inhibition of glial activation and expression of proinflammatory cytokines in a mouse model of Parkinson’s disease." (PMID 35281260, 2022). "For example, activation of TRPV1 channels, whose activation can both exacerbate and counteract some of the major symptoms in animal models of Parkinson’s and Huntington’s diseases, is the best-established non-CB1, non-CB2-receptor-mediating action of AEA." (PMID 33650014, 2021). "Another recent study has also reported that TrpV1 activation in astrocytes in a rat model of Parkinson’s disease is involved in the prevention of dopamine neuron degeneration in substantia nigra." (PMID 30417826, 2018). "Several studies have indicated that TRPV1 is involved in pain mechanisms in Parkinson’s disease." (PMID 38203538, 2023). "TRPV1 is considered to play a major role in the disruption of calcium homeostasis under inflammatory conditions, which is a strong likelihood in the development of many neurodegenerative processes and in particular the pathogenesis of Parkinson’s disease." (PMID 38203538, 2023). "Perhaps, blocking TRPV1 channels may prove to be a useful approach in the treatment of neurodegenerative diseases and Parkinson’s disease in particular." (PMID 33802055, 2021). "Moreover, TRPV1 inhibition was important for the neuroprotective effect of cannabidiol in another cell Parkinson’s disease model." (PMID 33802055, 2021). "For instance, the activation of TRPV1 in microglia can facilitate the phagocytic degradation of both Aβ and α‐synuclein aggregates by enhancing autophagic function, resulting in improved neuronal functions and behavioral performance in AD or Parkinson's disease mouse models." (PMID 37641913, 2024). "Additionally, research indicates that TRPV1 channels facilitate neuronal Glu release and increase EPSC frequency in brain regions such as the SSC and striatum, providing significant insights into the mechanisms underlying motor control disorders, including Parkinson’s and Huntington’s diseases." (PMID 41459513, 2025). "The present study examined whether crosstalk between cannabinoid (CB) and transient potential receptor vanilloid type 1 (TRPV1) could contribute to the survival of nigrostriatal dopamine neurons in the 1-methyl-4-phenyl-1,2,3,6-tetrahydropyridine (MPTP) mouse model of Parkinson's disease (PD)." (PMID 33062722, 2020). "The peptides did not modulate the TRPV1 channels but they affected the P2X7R, both of which are considered therapeutic targets in Parkinson’s disease." (PMID 35563513, 2022).
rheumatoid arthritis (19 papers, 2010 to 2026). A chronic, systemic autoimmune disorder characterized by inflammation in the synovial membranes and articular surfaces. "Autoimmune hepatitis, multiple sclerosis, type 1 diabetes, rheumatoid arthritis, and systemic lupus erythematosus are among the autoimmune diseases where TRPV1 has been implicated." (PMID 41569118, 2026). "The investigation of TRPV1’s involvement in autoimmune conditions such as systemic lupus erythematosus, multiple sclerosis, and rheumatoid arthritis highlights its potential as a therapeutic target." (PMID 41569118, 2026). "According to research, TRP channels have become drug targets for the treatment of RA as there are multiple TRP channels in rheumatoid arthritis synovial fibroblasts, including TRPV1, TRPA1, TRPC5, TRPM3, TRPM7, and TRPM8." (PMID 30792744, 2019). "Application of capsaicin concentrations that desensitize TRPV1 channels result in a decrease in pain and levels of these inflammatory peptides in oseteoarthritis and rheumatoid arthritis." (PMID 24798548, 2014). "The translational relevance of these findings is underscored by the growing clinical interest in TRPV1-targeted therapies for pain conditions such as rheumatoid arthritis and orofacial pain, where TRPV1 antagonists have shown efficacy in reducing both pain and inflammation." (PMID 40943453, 2025). "Furthermore, deletion of TRPV1 gene was shown to attenuate synovial inflammation, bone erosion, cartilage damage in the course of rheumatoid arthritis." (PMID 31681615, 2019). "TRPV1’s alterations have been found in other chronic pain diseases, including rheumatoid arthritis (RA), osteoarthritis, and IBS." (PMID 38928175, 2024). "Other TRPV1 agonists, like resiniferatoxin (RTX) found in the Euphorbia plant, have demonstrated analgesic effects in rheumatoid arthritis." (PMID 41569118, 2026).